CD4 (CD4 molecule)
Diseases named in the same sentence as CD4 in open-access papers (continued):
Sharing a sentence is not in itself a finding about the gene and the disease.
infection (continued). "Whereas the acute phase of the infection is dominated by virus-mediated depletion of memory CD4+ T cells, chronic infection is often associated with a progressive decline of total CD4+ T cells, including the naïve subset." (PMID 19360097, 2009). "Previous studies have established that a primary infection with cougar-derived strain PLV-1695 (PLV hereafter) protects cats from CD4 decline caused by subsequent infection with a virulent feline immunodeficiency virus (FIVfca) strain (FIVC36; FIVC hereafter)." (PMID 19806226, 2009). "Together, these observations support the importance of efficient coreceptor binding to the susceptibility of HIV-1 to SCM-induced activation of infection of CD4− cells." (PMID 19343205, 2009). "Studies in HIV infection have established that susceptibility to different infections is related to the degree of reduction in CD4+ T cell counts in the blood." (PMID 19943952, 2009). "There is supportive evidence, although weaker than that for the role of antibodies, that CS-specific CD4+ T cell responses are independently associated with protection against infection." (PMID 20042088, 2009). "SIV-infected natural hosts, such as African green monkeys (AGMs), retain stable CD4+ T cell counts in peripheral blood even in the presence of viral loads (VLs) as high as those observed during pathogenic infection." (PMID 19214219, 2009). "Most of these defects are considered as the hallmarks of the chronic phase of infection and are frequently correlated with increased plasma viral load (pVL) and loss of CD4+ cells." (PMID 19543531, 2009). "After the transient loss of memory CD4+ T cells, the naïve to memory CD4+ T cell ratio recovered to levels comparable to pre-infection ratios, with the exception of A7." (PMID 20011508, 2009). "HIV infection is associated with an increased disease-to-infection ratio at all stages of infection and with increased susceptibility to infection as CD4 count declines." (PMID 19159487, 2009). "Infection increased the proportion of CD69+ activated B cellsand CD4+ T cells in immune normal mice compared to IgD deficient mice." (PMID 19859584, 2009). "The ADCs cause a loss of CD4 memory cells that represent a component of the T-cell repertoire that is specific to most ADC infections." (PMID 19630949, 2009). "Apoptosis of both pulmonary and extrapulmonary lymphocytes is part of the normal host response to Pneumocystis but is also triggered in CD4-deficient animals with progressive infection." (PMID 19558669, 2009). "To compare the degree of Treg cell activation directly by the infection, the presence of pathogenic CD4+ T cells, or the transfer into lymphopenic Rag1−/− recipients, we further examined their individual or combined effect on Treg cell expansion." (PMID 19006695, 2008). "Concordant associations between CCL3L1-CCR5 genotype and recovery of CD4+ T cell counts were also observed in subjects who received HAART during acute/early infection." (PMID 18776933, 2008). "The identification of sites associated with high CD4+ counts and low viral loads at 12 months post infection." (PMID 18369479, 2008). "Here we describe the identification of two HIV-1 Gag polymorphisms that are associated with low viral loads and high CD4+ counts during both the acute and chronic phases of infection." (PMID 18369479, 2008). "Infection with HTLV-1 was associated with higher spontaneous IFNγ release by CD4+ T cells, but only in HAM/TSP there was a marked increase in T cell proliferation." (PMID 18664281, 2008). "Recently, it has been shown that a small subset (10–15%) of naturally infected SMs experience a significant loss of CD4+ T cells during the course of their infection." (PMID 18636106, 2008). "Although HIV can infect most CD4-expressing cells, particularly CD4 T helper cells, it is accepted that infection of this cell subset cannot solely explain the HIV-associated immunopathogenesis." (PMID 18698365, 2008).
infection (continued). "Granuloma formation requires CD4+ T cells as mice deficient in these cells fail to form granulomas or control the infection." (PMID 18560543, 2008). "It is thus possible that a Nef-mediated suppression of CD4+ T cell activation and cell death contributes to a general reduction of infection-associated immune activation." (PMID 18636106, 2008). "Our data demonstrated that patients coinfected with HCV and HIV-1 was associated with significant higher CD4+ T-cell counts than that in HIV-1 mono-infection group, furthermore, co-infected individuals also tended to have lower viral loads." (PMID 19098990, 2008). "Advantages of the RAG-hu model for studying HIV infection include its capacity to support chronic productive HIV infection for over 1 year, to display CD4 depletion and to being susceptible to infection by either vaginal or rectal routes." (PMID 18237418, 2008). "Here we investigate the relationship between the genotypes of transmitted viruses and prognostic markers of disease progression and show that infection with HLA-B*57/B*5801 escape mutants is associated with lower viral load and higher CD4+ counts." (PMID 18369479, 2008). "Examination of Gag sequences from acutely infected HLA-B*57/5801 negative women has revealed two polymorphisms, A146X and T242N, that are associated with lower viral loads and higher CD4+ counts in these woman up to a year post infection." (PMID 18369479, 2008). "Conversely, expression of Nef in MDDCs and neutralization of CD4 by antibodies decrease available surface CD4 and are associated with increases in trans-infection." (PMID 18584030, 2008). "For S. pneumoniae, HIV infection confers a 50-fold increased risk of infection, which is also inversely related to CD4+ T cell count." (PMID 18802458, 2008). "For instance, it was observed that IFNγ secreting CD4+ T cell responses developed earlier in patients with asymptomatic CMV infection than in patients with symptomatic infection and were associated with clearance of the virus." (PMID 19023425, 2008). "This switch is thought to occur in 50% of infections and is associated with an accelerated loss of CD4+ T-cells and progression to AIDS." (PMID 18312662, 2008). "A B cell response shifts to a CD4+ cell response as the infection progresses, and worm fecundity in B cell-deficient mice becomes comparable to that in B cell-intact mice." (PMID 18320044, 2008). "We next asked if CD4+ cells were involved in the failed granuloma development observed early in the infection of OBF-1-deficient mice." (PMID 18320044, 2008). "This was followed by reports on laboratory adapted HIV-1 variants that were able of CD4-independent infections." (PMID 17645788, 2007). "Higher baseline HIV-RNA levels in early infection have been associated with faster CD4+ T-cell decline over the first two years of infection." (PMID 17502001, 2007). "Following the first infection of a cell, viral gene expression induces CD4 down-modulation, which lowers the susceptibility of the cell to further infections." (PMID 17967052, 2007). "A higher value of td implies slower CD4 down-modulation, which renders infected cells susceptible to further infections for longer durations and hence increases the relative prevalence of multiply infected cells." (PMID 17967052, 2007). "A model of CCR5-tropic simian immunodeficiency virus (SIV) infection that induces acute loss of memory CD4+ T cells like HIV infections in humans would be adequate for assessment of post-infection NAb efficacies in primary immunodeficiency virus infection." (PMID 17579714, 2007). "Regression analyses were used to estimate associations between pre-infection vitamin E and plasma viral load, time to CD4 count <200 cells/μL, and mortality." (PMID 17594484, 2007). "Advanced HIV infection, marked by very low numbers of CD4+ cells, is associated with a variety of infections and tumors that are rarely seen in people with intact immune systems." (PMID 17388662, 2007).
infection (continued). "In a previous study of Vietnamese IDU EUs we identified some individuals whose CD4 T lymphocytes showed reduced susceptibility to in vitro infection by replicative strains of HIV-1." (PMID 17092330, 2006). "These macaques experienced a significant decline in CD4+ T cells associated with SIVmac055 infection and displayed typical clinical and pathological features consistent with simian AIDS." (PMID 17184540, 2006). "Recent studies have confirmed that acute HIV infection results in a rapid and profound loss of memory CD4+CCR5+ T cells within the first few weeks of infection." (PMID 17147469, 2006). "Our laboratory has shown that primary cultures of mammary epithelial cells (MEC) – that are possibly implicated to the mother-to-child transmission of infection – do express surface CD4, galactosylceramide and CD26 and can be infected by HIV-1." (PMID 15857508, 2005). "Infection of transfected HeLa cells with a vaccinia virus recombinant encoding T7 RNA polymerase allowed higher expression levels of the chimeric CD4 proteins in an increased number of cells." (PMID 16371160, 2005). "The risk of infection is related to treatment with systemic steroid, ill-defined individual variation in steroid sensitivity and CD4+ lymphocyte count." (PMID 15488151, 2004). "Notably, cleavage-deficient Env can support CD4-dependent, cell-to-cell viral transfer, indicating that uncleaved cell surface Env can participate in early events of cell‐to‐cell infection." (PMID 42207948, 2026). "Targeting lung innate pathways in BCG-vaccinated DO mice using adjuvants also further improved protection upon Mtb infection by inducing genes associated with cellular responses to external stimuli, B-cell responses, as well as IL-17-producing CD4+ T-cell responses." (PMID 41556657, 2026). "They correlated CD4 reconstitution with thymic function (using T cell receptor excision circles) and showed that a higher number of recent thymic emigrants (i.e. higher levels of excision circles) correlated with lower risk for cancer and infection." (PMID 40612959, 2025). "In line with literature reports of worse clinical outcomes in PLWH presenting in advanced stages of infection, prior studies demonstrated that the degree of gastrointestinal impairment, gut-dependent inflammation, and dysbiosis are linked to the CD4+ T-cell nadir." (PMID 41267933, 2025). "This unexpected inhibitory effect of Themis on TFH cell differentiation at late stage of infection essentially explains our other finding that transfer of Themis-deficient CD4+ T cells helps control persistent viruses by enhancing GC responses and antibody production." (PMID 40777021, 2025). "The decline in the proportion of CD4+ CD8+ T cells also elevates the risk of infection, as T cell exhaustion may impair their normal function." (PMID 41142813, 2025). "However, prolonged inflammation in the lung and airways persisted up to day 28 post‐infection and was associated with the presence of CD4+ and CD8+ T cells, particularly CD8+ effector T cells." (PMID 40851359, 2025). "The influence of CD4+ T cell depletion on human coronavirus (HCoV) (re)infection risk, including SARS-CoV-2, is largely unknown." (PMID 40531922, 2025). "Finally, the large amount of missing data on CD4 and viral load hindered our ability to fully explore associations between immunovirological control and infection risk." (PMID 40663570, 2025). "Moreover, neutrophils secrete chemokines and cytokines that actively recruit CD4 + T cells – the primary targets of HIV – into sites of infection, inadvertently expanding the pool of susceptible cells and facilitating viral propagation." (PMID 40901106, 2025). "Decreased frequency of naïve CD4 T cells was strongly associated with infection (p=0.027) (Post)." (PMID 40475763, 2025). "CD4+ cell monitoring is crucial for predicting infection risk and guiding clinical management." (PMID 40943696, 2025).
infection (continued). "Interestingly, polyfunctional CD4 T-cell responses showed a weak correlation with lower infection risk when interacting with the antibody responses." (PMID 40733667, 2025). "To test the role of Tet1/3 in CD8 effector T-cell fates during acute LCMV-Armstrong infection, we challenged RorcCreTg Tet1/3fl/fl mice (hereafter referred to as Tet1/3cDKO), in which double-positive thymocytes and their αβ CD4+ and CD8+ single positive progenies are deficient in Tet1 and Tet3." (PMID 40175595, 2025). "Moreover, ciTRAN expression was elevated either by treatment with recombinant TGF-β1 or by infection of primary CD4+ T cells by NLBN-zsGreen reporter virus encoding Vpr and was reversed by treatment with Repsox." (PMID 40632811, 2025). "We reviewed medical records and interviewed 452 adults newly diagnosed with HIV to determine the proportion of recent vs. long-term infections, identify socio-behavioral factors associated with recent infection and examine predictors of viral load and CD4 count." (PMID 41229481, 2025). "A CD4+ cell count > 500 was inversely associated with high-risk genotype (OR: 0.48; 95% CI: 0.27–0.86; p = 0.013) and low-risk genotype (OR: 0.45; 95% CI: 0.24–0.83; p = 0.010) infections." (PMID 40872859, 2025). "Therefore, a robust CD4+ T cell response is associated with a favorable outcome after infection, highlighting the importance of eliciting this response as an archetype for a successful vaccine." (PMID 40739075, 2025). "The results showed that a CD4 + T-cell count below 200 cells/μL was a strong independent risk factor for infection with both C. parvum (adjusted odds ratio [aOR] = 8.4; 95% confidence interval [CI]: 3.2–21.7; p < 0.001) and E. bieneusi (aOR = 6.5; 95% CI: 2.1–19.6; p = 0.002)." (PMID 41372782, 2025). "In contrast, it was detected in only 2% of the control group and also in another study involving HIV-positive patients that revealed that Blastocystis hominis infection decreased progressively with increasing CD4+ T-helper cells, while the risk of infection increased with higher HIV viral load." (PMID 40430744, 2025). "This is may be due to a multitude of reasons, such as immunosuppression resulting from low CD4 cell counts, increased high‐risk sexual behavior, or an immune response to anal lesions that may in turn mediate infection with rare HPV types." (PMID 40172095, 2025). "However, anti–P selectin treatment during infection was associated with a shift in brain-resident T cell populations, characterized by increased CD4+ and decreased CD8+ T cells." (PMID 41243963, 2025). "However, depletion of CD4 T cells rescued OMM12 animals from more severe body weight loss at day 4 after infection." (PMID 40274773, 2025). "However, the substantial amount of missing data on CD4 count and viral load limits the strength of conclusions regarding the association between poor immunovirological control and infection risk." (PMID 40663570, 2025). "Several studies have shown that the hormonal and immunologic changes occurring in women during pregnancy lead to a decrease in the proinflammatory activity of CD4+ lymphocytes, which leads to increased susceptibility to infection, TB reactivation, and causes its low-symptomatic course." (PMID 39981081, 2025). "A noticeable shift was seen in CD4+ T cells toward T helper 1 (Th1) polarization, which corroborates a massive increase in the expression of Th1-associated cytokines and chemokines at the peak of infection, indicative of an augmented proinflammatory state." (PMID 39907280, 2025). "Strong cytotoxic CD4+ T cell responses early in the infection were linked to defects in B cell responses, implying iCope‐ and therefore pan‐coronavirus‐specific T cells with cytotoxic properties might be a risk factor for severe disease." (PMID 40726062, 2025). "Additionally, these strategies led to the generation of newly activated CD4+ T cells—the preferred target of HIV—accentuating the risk of infection." (PMID 38543734, 2024).
infection (continued). "Interpreting our probabilistic output through median log10 SpVL and the proportion of individuals with greater than 350 CD4+ T cells mm–3, we found that both end-points were similar between multiple and single variant infections and varied only slightly across risk groups." (PMID 39471873, 2024). "We speculate that defects in CD4+ T cell activity, proliferation and differentiation may increase susceptibility to and facilitate secondary infections, while the inflammatory state of CD4+ T cells could worsen organ damage." (PMID 39266539, 2024). "Compared to Rag1‐KO mice that received either PBS or non‐manipulated naïve CD4+ T cells from old mice, Rag1‐KO mice that received mito‐transferred naïve CD4+ T cells from old mice had a significant delay in IAV‐induced morbidity (weight loss) by day 8 post‐infection." (PMID 37990641, 2024). "In addition, homozygous CC genotypes for rs1799964 (TNF) were associated with higher CD8+ and lower CD4+ T-cell counts compared to some individuals with HIV mono-infection group." (PMID 39066175, 2024). "Last, we hypothesized that the proximity of follicular CD4+ T cells to highly susceptible B cells in the follicle could affect the susceptibility of these CD4+ cells to infection." (PMID 39253971, 2024). "A study in guinea pigs used topical imiquimod, which recruited both CD8 and CD4 cells; increased numbers of CD4 cells in the genital mucosa could potentially increase the risk of infection with HIV." (PMID 38690731, 2024). "The upregulation of CD52 in CD4+ T cells in AD impairs antigen-specific T cell responses and thus potentially contributes to immunoparesis in AD, which leads to an increase in the risk of infection and mortality." (PMID 39276679, 2024). "However, most studies evaluating the role of genital DCs in HIV pathogenesis have investigated events that occur 12 hours or more after viral exposure, focusing on DC susceptibility to HIV infection and trans-infection to CD4+ T cells." (PMID 39524443, 2024). "In contrast, Cd4−/− mice showed increased susceptibility to a broad range of experimentally induced pathogen infections, including Staphylococcus aureus, lymphocytic choriomeningitis virus, Cryptococcus neoformans, Mycobacterium tuberculosis, rotavirus, prions, Ehrlichia, or hepatitis virus." (PMID 38557723, 2024). "To understand whether skin and systemic immunity observed after repeated IN infections are associated with the induction of immune responses in the spleen, we analyzed splenic CD4+ T cells and neutrophils using immunohistochemistry (IHC) staining." (PMID 38576622, 2024). "Therefore, we conformed that CD4+T cells exerted predominant influence on anti-infection responses when loss of TIGIT." (PMID 38545097, 2024). "Thus, the abnormal differentiated CD4+ T cell subsets were implicated with perioperative infection and poor clinical outcomes." (PMID 39266539, 2024). "In this study, we sought to understand whether the significant association between multiple variant infection, log10 SpVL or faster CD4+ T cell decline could be recapitulated using available data, in the absence of an explicit dependency." (PMID 39471873, 2024). "Conversely, the decrease detected in CD4+ T cells for NPS+ neonates agrees with published data, suggesting a possible immunopathogenic pathway of SARS-CoV-2 infection, even if it is difficult to conclude that the decrease in CD4 can certainly be caused by an infection." (PMID 38416109, 2024). "Immune suppressive drugs as corticosteroids that reduce T-cell response, particularly CD4+cells, even at low-dose, may confer increased risk of infection especially in patients with chronic immune-mediated inflammatory diseases (IMIDs)." (PMID 38965547, 2024). "Additionally, the presence of Env-specific CD4+ T cells was found to be inversely correlated with the risk of infection, further emphasizing the importance of cellular immune responses in vaccine-induced protection." (PMID 38543734, 2024).